RNF168 (ring finger protein 168)
Diseases named in the same sentence as RNF168 in open-access papers (continued):
Sharing a sentence is not in itself a finding about the gene and the disease.
tumor (17 papers, 2011 to 2025). "The analysis of RNF8- and RNF168-deficient mice further supports a role of these key E3 ligases in tumor suppression." (PMID 26442100, 2015). "Notably, in ESCC patients, increased RNF168 expression was associated with tumor stage and depth of invasion." (PMID 33493132, 2021). "Nuclear p62 directly binds to RNF168 and inhibits RNF168 mediated histone H2A ubiquitination and DNA damage responses, thus increasing the sensitivity of tumor cells to radiation." (PMID 39487119, 2024). "Since several studies have observed that the Wnt/β-catenin signaling pathway upregulates the expression of glycolytic enzymes, abundant RNF168 triggers glycolysis in tumor cells." (PMID 37176148, 2023). "Overexpression of RNF168 in tumor cells also induces abnormal DNA repair, imbalancing this repair pathway and resulting in cancer." (PMID 37176148, 2023). "In summary, RNF168 has important value in the drug resistance of tumor cells and the development of anticancer drugs." (PMID 36771081, 2023). "The mechanism underlying selective elimination of tumor cells with compromised UBE2N- and RNF168-mediated ubiquitination, upon exposure to G4 ligands, was further characterized." (PMID 33963218, 2021). "RNF168 expression was high in 38 (49.2%) of the tumor tissues but only in 4 (5.8%) of the adjacent normal tissues." (PMID 33493132, 2021). "The observations presented above stronglysuggest a broader role in the regulation of cell fate, i.e. in controlling cellsurvival and proliferation (–5).It is arguable that the amplification of RNF168 in tumours isconsistent with this wider role." (PMID 28754805, 2017). "We observed that knockdown of RNF168 in the tumour cell lines T47D and MDA-MB-231 restrained ubiquitylation of their endogenous TOP2α." (PMID 27558965, 2016). "Additionally, RNF168 contributes to the drug resistance of tumor cells by enhancing their DNA repair ability or regulating the degradation of target proteins." (PMID 36771081, 2023). "RNF168 depletion led to a further increase of R-loop levels and reduced tumour formation in BRCA1-mutated cells, indicating a functional role of DHX9 ubiquitylation in R-loop resolution and tumour formation of BRCA1-deficient backgrounds." (PMID 33755171, 2021). "Therefore, more data are needed to determine the function of RNF168 in tumor progression." (PMID 36771081, 2023). "Therefore, the role of RNF168 in BRCA1 mutant tumor cells needs further study, such as on RNF168, which may need to reach a certain protein level to serve as an oncogene." (PMID 36771081, 2023). "Notably, RNF168 expression levels correlated with clinicopathological features of the tumor, such as pathological staging and depth of invasion, indicating that RNF168 may serve as a biomarker of malignancy in ESCC." (PMID 33493132, 2021). "S6K and RNF168, common downstream factors in the PI3K/Akt/mTOR pathway that influence tumor proliferation and migration, were significantly upregulated in mice treated with the AKT activator." (PMID 40328748, 2025). "Depletion of the tumor suppressor LKB1 activates mTORC1 and decreases RNF168 abundance, subsequently impairing DDR." (PMID 39487119, 2024). "In summary, our study demonstrates for the first time that RNF168 is highly expressed in human ESCC and that it correlates with the depth of tumor invasion and pathological staging, suggesting its potential use as a marker of ESCC malignancy." (PMID 33493132, 2021). "To examine whether inactivation of Rnf168 predisposes for tumor development, we monitored cohorts of Rnf168+/+ (n = 56) and Rnf168−/− (n = 52) mice for a period of 12 months; however, none of the monitored Rnf168−/− mice developed tumors during the 1 year period." (PMID 21552324, 2011). "The SUMOylated RNF168 catalyzed by SENP1 prevents the occurrence of LLPS, allowing RNF168 to be recruited to DNA damage sites for nonhomologous DNA end-joining, thereby maintaining genomic stability and even making tumor cells resistant to chemotherapy." (PMID 39749343, 2024).
tumor (continued). "In patients with ESCC, RNF168 expression was not correlated with gender, age, degree of differentiation, tumor size, lymph node metastasis, or distant metastasis, but did correlate with pathological stage and depth of invasion." (PMID 33493132, 2021). "Hence, we speculated that RNF168 may participate in this process by ATM, and therefore activate the physiology and proliferation of tumor cells." (PMID 33493132, 2021).
infection (3 papers, 2011 to 2026). The state of being infected such as from the introduction of a foreign agent such as serum, vaccine, antigenic substance or organism. "This implies that the reason ICP0 targets RNF8 and RNF168 for degradation is to prevent recruitment of specific DNA repair factors to viral genomes, suggesting that this recruitment is detrimental to incoming virus during early stages of lytic infection." (PMID 21698222, 2011). "During infection with wild-type virus, ICP0 expression prevented 53BP1 recruitment in the presence or absence of RNF8 and RNF168." (PMID 21698222, 2011).
RNF168 also shares sentences with these, for which no sentence is quoted: thymoma (2 papers); Ataxia (1); Bloom syndrome (1); Cohen syndrome (1); FILS syndrome (1); ICF syndrome (1); Kabuki syndrome (1); lymphopenia (1); myocardial infarction (1); sarcoma (1); Sepsis (1); squamous cell carcinoma (1); testicular embryonal carcinoma (1); thymic lymphomas (1); triple-negative breast carcinoma (1); Xeroderma pigmentosum complementation group C (1).